KRTAP10-5 (keratin associated protein 10-5)
Description:
In the hair cortex, hair keratin intermediate filaments are embedded in an interfilamentous matrix, consisting of hair keratin-associated proteins (KRTAP), which are essential for the formation of a rigid and resistant hair shaft through their extensive disulfide bond cross-linking with abundant cysteine residues of hair keratins. The matrix proteins include the high-sulfur and high-glycine-tyrosine keratins.
Synonyms: KAP10.5; KAP18-5; KRTAP10.5; KRTAP18-5; KRTAP18.5; KAP18.5; KRTAP18.1
Tractability: No criterion of Open Targets' tractability assessment is met for any kind of drug.
Gene: Protein-coding gene on chromosome 21 (44,579,455 to 44,580,604, reverse strand). Ensembl gene ENSG00000241123.
Pathways (Reactome):
Developmental Biology: Keratinization
Gene Ontology:
Molecular function: identical protein binding; protein binding
Cellular component: cytosol; keratin filament
Genetic constraint (gnomAD): Loss-of-function variants: 2 observed, 2.16 expected, observed/expected ratio (o/e) 0.93, 90% interval 0.35 to 1.86. That is too few expected variants to judge how well the gene tolerates losing a copy. Missense variants: 370 observed, 355.05 expected, observed/expected ratio (o/e) 1.04, 90% interval 0.96 to 1.14. Synonymous variants: 157 observed, 150.52 expected, observed/expected ratio (o/e) 1.04, 90% interval 0.92 to 1.19.
Homologues: Orthologues: chimpanzee KRTAP10-5 (94% identical). Paralogues in human: KRTAP10-1 (92% identical), KRTAP10-9 (85% identical), KRTAP10-11 (84% identical), KRTAP10-7 (82% identical), KRTAP10-4 (81% identical), KRTAP10-6 (77% identical), KRTAP10-2 (76% identical), KRTAP10-10 (69% identical), KRTAP10-12 (68% identical), KRTAP10-3 (65% identical), KRTAP10-8 (63% identical), KRTAP4-12 (34% identical), and 35 more.